SNORD115-27 (small nucleolar RNA, C/D box 115-27)
Synonyms: HBII-52-27
Gene: Small nucleolar RNA gene on chromosome 15 (25,220,497 to 25,220,578, forward strand). Ensembl gene ENSG00000201300.
Gene Ontology:
Biological process: RNA processing
Cellular component: nucleolus
Homologues: Orthologues: chimpanzee SNORD115 (99% identical), macaque SNORD115 (91% identical). Paralogues in human: SNORD115-12 (91% identical), SNORD115-9 (91% identical), SNORD115-1 (90% identical), SNORD115-10 (90% identical), SNORD115-11 (90% identical), SNORD115-13 (90% identical), SNORD115-20 (90% identical), SNORD115-29 (90% identical), SNORD115-36 (90% identical), SNORD115-37 (90% identical), SNORD115-40 (90% identical), SNORD115-42 (90% identical), and 37 more.